CDKN2A (cyclin dependent kinase inhibitor 2A)
Diseases named in the same sentence as CDKN2A in open-access papers (continued):
Sharing a sentence is not in itself a finding about the gene and the disease.
tumor (continued). "This study suggests that CDKN2A/p16 alteration may contribute to the low fibrotic ECM formation, independent of tumor progression, in PDAC." (PMID 37477731, 2023). "Moreover, differential CDKN2A and LIAS methylation levels were noted in the tumor and adjacent nontumor tissues." (PMID 36092958, 2022). "The relationship of CDKN2A and CDKN2B expression with the corresponding SCNA levels seemed to indicate that complex pathways regulated their transcription levels and that their tumor suppressor properties were not evident in ccRCC." (PMID 35677048, 2022). "Promoter methylation levels of MLH1, MGMT, CDKN2A, and RASSF1A genes were not increased in cancer with respect to healthy tissues and did not correlate with the histological or pathological features of the tumor or with the MG symptoms." (PMID 33192293, 2020). "In addition, his tumor tissue was negative for both p15 (coded by CDKN2B) and p16 (coded by CDKN2A) by immunohistochemistry (IHC) staining." (PMID 31700061, 2019). "While the parental HPDE cell line does not form tumours after orthotopic transplantation, expression of oncogenic KRASG12V and ERBB2 combined with short hairpin RNA-mediated knockdown of CDKN2A and SMAD4 produced lesions resembling invasive PDA after transplantation." (PMID 28272465, 2017). "Also, CDKN2A and XRCC5, which are TSGs involved in DNA repair, displayed high hypermethylation intensities and, unlike MLH1, were altered in all tumor types." (PMID 28581523, 2017). "The comparison of the findings in the tumor tissue and in the peripheral blood from the same patient showed no RASSF1 or CDKN2A methylation in any of the peripheral blood samples, and only one sample positive for MGMT methylation; a T4N0 M0 (stage IVa) squamous cancer of the oral cavity." (PMID 19807915, 2009). "This microsatellite is 8 kb away from CDKN2A exon 1β and 3 kb from CDKN2B exon 2, which could not be detected in the tumour DNA." (PMID 19643034, 2009). "The possible presence of LOH in CDKN2A and DCC may increase the likelihood of tumours being non-informative for these two markers." (PMID 18594522, 2008). "The expression levels of 14-3-3σ, CDKN2A and ARF were not correlated with but rather reciprocal to one another, suggesting that simultaneous overexpression of any two of them is incompatible with tumor growth." (PMID 18036248, 2007). "Notably, CDKN2A/B deletions can be identified in tumours with as few as 6 or more mitotic figures per 10 HPF, but tumours with high mitotic counts may not necessarily have CDKN2A/B deletion." (PMID 40356449, 2025). "Importantly, four of the eight tumours with CDKN2A/B homozygous deletion were well-defined, four demonstrated ≥25% T2-FLAIR mismatch, only one demonstrated solid enhancement (with two further tumours demonstrating wispy enhancement), and none had MRI evidence of necrosis." (PMID 37316586, 2023). "Microarray analysis revealed the CDKN2A and CDKN1A genes to be significantly repressed in all tumour types vs controls while the CDK2 gene was upregulated in the all tumours vs controls and CDK6 was also upregulated in GH-secreting tumours vs controls (data not shown)." (PMID 28649092, 2017).
cancer (2,070 papers, 1996 to 2026). A tumor composed of atypical neoplastic, often pleomorphic cells that invade other tissues. "We found that 22.2–100% of CDKN2A missense somatic mutations were functionally deleterious depending on cancer type." (PMID 40238651, 2025). "Mutations in the CDKN2A gene often lead to loss of anti-cancer activity of CDKN2A, thus promoting cell proliferation and tumorigenesis." (PMID 41341386, 2025). "Our results would also suggest a loss of H3K27me3 in cancers that lose the G1 checkpoint via mutations in Rb or deletions in Cdkn2a." (PMID 40245079, 2025). "Mutations, copy number variations, and methylation of CDKN2A have been associated with several cancer types." (PMID 40507266, 2025). "Chan S., Chiang J., Ngeow J. CDKN2A germline alterations and therelevance of genotype-phenotype associations in cancer predisposition.Hered Cancer Clin Pract." (PMID 40584241, 2025). "As CDKN2A VUSs will continue to be identified in patients with cancer undergoing genetic testing, we developed a high-throughput functional assay to provide a broad interpretation framework for CDKN2A variants." (PMID 38234851, 2025). "Although varied amoung cancers, more than 80% of MTAP-loss cancers also display codeletion of CDKN2A." (PMID 41583489, 2025). "CDKN2A, encoding the tumor suppressors p16 and p14ARF, is one of the most frequently homozygously deleted genes across all human cancers, and acts as an inhibitor of cuproptosis." (PMID 40083663, 2025). "At least three silencing modalities of CDKN2A (pure deletion, promoter methylation, and point mutations) are associated with poorer clinical outcomes in some cancers." (PMID 39253931, 2025). "Inspired by the high frequency of aberrant DNA methylation occurrence in EBV‐associated cancers, we analyzed the details of CDKN2A methylation status in all six CpG islands and revealed its diversity among different kinds of GCs." (PMID 39844467, 2025). "In most cancer types, MTAP deficiency is caused by homozygous co-deletion with cyclin dependent kinase inhibitor 2A (CDKN2A) gene at 9p21.3 which is homozygously deleted in up to 15 % of all human cancers." (PMID 40554389, 2025). "The next suppressor gene that is mutated in different types of cancer is CDKN2A, which encodes the p16 protein." (PMID 39361216, 2025). "A Dutch cohort study demonstrated a rapid growth of cancers in the pancreases of CDKN2A/p16 variant carriers, in which a cystic precursor lesion was absent in nearly half of the cases." (PMID 38961426, 2024). "Mutations in CDKN2A were associated with worse recurrence-free survival (HR: 5.76; p < 0.001) and worse cancer-specific survival (HR: 2.94; p = 0.03) in multivariable analyses." (PMID 39768623, 2024). "CDKN2A inactivation is linked to the development of cancer via three primary mechanisms: suppression of RNA polymerase activity, alteration of chromatin structure, and prevention of transcription factor binding to DNA." (PMID 38206516, 2024). "For example, a cancer-associated missense mutation in the CDKN2A gene produces a protein variant of one of its protein products, p16INK4A, in which alanine at position 20 is substituted with proline (p16INK4A A20P)." (PMID 38713862, 2024).
cancer (continued). "The comparison of these findings from both databases showed the three most common cancers associated with high CDKN2A expression." (PMID 38894777, 2024). "Although CDKN2A alteration has been explored as a favorable factor for tumorigenesis in pan-cancers, the association between CDKN2A point mutation (MUT) and intragenic deletion (DEL) and response to immune checkpoint inhibitors (ICIs) is still disputed." (PMID 38822443, 2024). "CDKN2A, as a cell cycle regulation gene, is associated with cuproptosis processes and is shown to impact cancer patients’ prognosis." (PMID 38728242, 2024). "The analysis of 11 biomarkers associated with well-known cancer signaling pathways revealed that CDKN2A was characterized by the lowest abundance, while EGFR exhibited the highest expression." (PMID 38956740, 2024). "It is assumed that epigenetic changes in CDKN2A have been linked to genetic or epigenetic changes in other cancer-related genes." (PMID 39590385, 2024). "Discovered in 1994, the CDKN2A gene, encoding the cell-cycle inhibitor p16, shows somatic mutations in various cancers." (PMID 38666907, 2024). "CDKN2A inactivates the pRb with subsequent loss of cell cycle control, genome instability, and increased proliferation followed by transformation to cancer." (PMID 39712018, 2024). "Mutations in CDKN2A can lead to the loss of growth control in several cancers, including BRCA, ovarian cancer (OC), and head and neck squamous cell carcinoma (HNSC)." (PMID 39702350, 2024). "CDKN2A, a critical tumor suppressor gene located on chromosome 9, encodes proteins such as p16(INK4A) and p14(ARF), playing pivotal roles in regulating diverse cancer-related processes." (PMID 38666907, 2024). "Subsequently, a pan-cancer survival analysis uncovered a consistent association between CDKN2A ALT and inferior OS in various cancer types." (PMID 38822443, 2024). "Loss of CDKN2A function is a common prerequisite for many cancers and is associated with shorter overall survival (OS) in patients with iCCA." (PMID 38877653, 2024). "Studying mutations in the CDKN2A gene is key to understanding the complex nature of cancer development." (PMID 38137564, 2023). "And the associations between CDKN2A expressions and prognosis in different cancer patients were evaluated in this study." (PMID 36961395, 2023). "The aim of this study is to provide a description of the genetic and clinical characteristics observed in carriers of CDKN2A genetic variants diagnosed with malignant neoplasms." (PMID 38137564, 2023). "Gene Set Enrichment Analysis is the main method used to search the associated cancer hallmarks associated with CDKN2A." (PMID 36961395, 2023). "Approximately 15% of cancers exhibit loss of the chromosomal locus 9p21.3 – the genomic location of the tumour suppressor gene CDKN2A and the methionine salvage gene methylthioadenosine phosphorylase (MTAP)." (PMID 37795443, 2023). "The components of this pathway, especially the CDKN2A gene encoding the p16Ink4a protein and RB, are often altered in sporadic human cancer, contributing to the dysregulation of cell proliferation." (PMID 37240140, 2023).
cancer (continued). "Understanding the spectrum of mutations affecting CDKN2A is critical to identifying their role in cancer susceptibility and progression." (PMID 38137564, 2023). "Results of disease-Free Interval (DFI) and Progression-Free Interval (PFI) analysis were also examined to adequately demonstrate that CDKN2A is a risk factor for most cancer types and is significantly associated with the prognosis of cancer." (PMID 36961395, 2023). "Although CDKN2A showed a high mutation frequency in various cancers, the expression of CDKN2A was overexpressed in many tumors and associated with immunosuppression and poor prognosis." (PMID 37287976, 2023). "Analysis of high-risk cancer pedigrees identified in this powerful Utah resource previously provided the identification of BRCA1 and BRCA2, and CDKN2A, which remain the most common cancer predisposition genes to be identified." (PMID 37046747, 2023). "There’s new evidence that genes inside the CDKN2A / B locus genes were mutated or deleted in several human cancers." (PMID 37845622, 2023). "Other than deletion or mutation of the Rb1 gene, the most frequent mutation locus in human cancers that disables the RB pathway is the CDKN2A locus coding for the p16INK4a CDK inhibitor (CKI)." (PMID 38132337, 2023). "The human CDKN2A locus, which encodes p16INK4A, is frequently inactivated or epigenetically suppressed in various types of cancers." (PMID 36706133, 2023). "CDKN2A was the most frequently mutated PCD gene across all cancer types, and exhibited the most diverse mutation profile, indicating that SNVs in CDKN2A are ubiquitous in multiple cancers." (PMID 37534256, 2023). "CDKN2A/B co-deletion was seen across multiple cancer types and was associated with both local recurrence and more rapid distant CNS recurrences after surgical resection of brain metastases." (PMID 36915611, 2023). "Though upregulated in one sample, the missense variant in CDKN2A was identified as a cancer mutation hotspot." (PMID 37810779, 2023). "CDKN2A displayed higher mutation rates across multiple cancer types (31%), and other frequently mutated genes included LRPPRC (13%), PRKAA2 (11%), VLDLR (9%), ASNS (8%), GZMA (7%), GLS (7%), TNFRSF1A (6%), PSAT1 (5%), and PRDX6 (4%)." (PMID 37534256, 2023). "Ultimately, the study of CDKN2A mutations not only enhances our basic understanding of cancer biology, but also provides concrete opportunities to advance personalized cancer therapy." (PMID 38137564, 2023). "The CDKN2A gene (chromosome 9p21) encodes the protein p16INK4a (also known as p16) through alternative exon usage, and this gene is the second most commonly inactivated tumour suppressor gene in cancer and is lost in the majority of chordomas." (PMID 38024139, 2023). "For example, the homozygous deletion of CDKN2A, which encodes p16, is pathognomonic for increased aggressiveness in glioma and other cancers." (PMID 36831620, 2023). "Loss of p16 (CDKN2A) expression in cancer cells was significantly associated with lymphovascular invasion and metastatic disease." (PMID 35565450, 2022). "Its encoding gene, CDKN2A, is localized on a chromosomal region 9p21.3, frequently deleted in human cancers." (PMID 35456025, 2022). "CDKN2A hypermethylation is a common event in cancer and had been previously associated with the TCGA CIMP samples." (PMID 36455002, 2022). "We identified nearly statistically significant mutual exclusivity between mutations in FAM84B and CDKN2A in various cancer types (P = 0.08)." (PMID 35396552, 2022). "Previous studies found that the causes of CDKN2A inactivation in various cancers were mainly point mutation, homozygous deletion or promoter hyper-methylation." (PMID 35637955, 2022).
cancer (continued). "CDKN2A loss by promoter hypermethylation has been demonstrated in a number of cancers, including GEP-NENs." (PMID 35747820, 2022). "On the other hand, CDKN2A loss either by genetic alterations or epigenetic gene silencing is one of the most frequent events in cancer, which allows precancerous cells to bypass senescence for tumorigenesis." (PMID 35484199, 2022). "CDKN2A deep deletion is associated with downregulation of CDKN2A gene expression, while CDKN2A amplification is associated with upregulation of CDKN2A gene expression in Pan-TCGA cancers." (PMID 36531022, 2022). "We find that known cancer driver genes such as CDKN2A and CREBBP are mutated in age-associated frequencies, and these alter the transcriptome and predict for clinical outcomes." (PMID 35017538, 2022). "It is important to highlight that the RPE1 cells used in this study, although telomerase immortalized and non‐transformed, do still have mutations in at least two known cancer‐associated genes: CDKN2A and KRAS." (PMID 35037284, 2022). "With the exception of CDKN2A, which carried few mutations overall, all genes carried high levels of cancer driver mutations ranging from 40% in ARID1A to 85% in KRAS." (PMID 36311816, 2022). "Examples of disease associated ankyrin proteins include cell cycle inhibitor p16 (CDKN2A), which is associated with cancer and Notch protein, a key component of cell signaling pathways that is associated with the neurological disorder CADASIL." (PMID 35056738, 2022). "These drugs are considered magic bullets against CDKN2A-deficient cancers and have demonstrated promising results in preclinical/clinical settings." (PMID 35155432, 2022). "Recent studies found that genomic CDKN2A loss-of-function is associated with worse clinical outcome in patients treated with cancer immunotherapy in multiple cancer types." (PMID 35155432, 2022). "In pan-cancer mutation analysis according to cBioPortal, CDKN2A showed the highest mutation types with deep deletions, followed by TERT, TRIM, and ZBP with a frequency of 11% amplifications." (PMID 35911707, 2022). "Loss of CDKN2A/p16INK4A expression is both an early event in the transition from premalignant to malignant tumors as well as a late event in the transition from localized to metastatic disease." (PMID 35304445, 2022). "We estimated a total SNV frequency of 98.23% of cuproptosis genes in pan-cancer, among which the top gene in mutation frequency was CDKN2A (42%)." (PMID 36212447, 2022). "Four carcinomas exhibited a missense mutation in the tumour suppressor CDKN2A, which was thus the second most frequently mutated gene." (PMID 35884448, 2022). "In this result, these commonly related genes including TERT, KRAS, and CDKN2A were also highly associated with cancer progression." (PMID 34442467, 2021). "As for CNV loss, deletion of CDKN2A/CDKN2B on chromosome 9 was associated with multiple drugs in multiple cancer types." (PMID 33741950, 2021). "We employed plucked human hair from two siblings with a family history of cancer carrying a pathogenic CDKN2A variant, P16-p.G101W/P14-p.R115L, to generate patient-specific iPSCs in a cancer-prone ancestry for downstream analytics." (PMID 34680288, 2021). "The CDKN2A gene encodes multiple tumor suppressor 1, which regulates various cancers through different biological processes." (PMID 35004697, 2021). "Recent studies have shown that CDKN2A gene is associated with poor prognosis in a variety of cancers, such as pancreatic cancer, bladder cancer, and pancreatic ductal adenocarcinoma." (PMID 34405225, 2021).